RNU6-923P (RNA, U6 small nuclear 923, pseudogene)
Gene: Small nuclear RNA gene on chromosome 5 (33,888,056 to 33,888,162, reverse strand). Ensembl gene ENSG00000201623.
Homologues: Orthologues: chimpanzee U6 (97% identical), macaque U6 (92% identical), rat U6 (86% identical). Paralogues in human: RNU6-11P (87% identical), RNU6-1209P (87% identical), RNU6-1243P (87% identical), RNU6-37P (87% identical), RNU6-1329P (86% identical), RNU6-16P (86% identical), RNU6-20P (86% identical), RNU6-25P (86% identical), RNU6-29P (86% identical), RNU6-797P (86% identical), RNU6-1 (85% identical), RNU6-1094P (85% identical), and 1289 more.